TNF (tumor necrosis factor)
Diseases named in the same sentence as TNF in open-access papers (continued):
Sharing a sentence is not in itself a finding about the gene and the disease.
breast tumor (continued). "Moreover, the correlations identified in our ex vivo cellular model (endothelial cells) between the expression of TNF-α mRNA and the expression of 19 putative TNF-α- inducible NF-κB target genes were also observed in human breast tumors." (PMID 21754991, 2011). "The breast tumour cell lines studied constitutively secreted low levels of TNFα, and this was not increased by the addition of 200 ng/ml IL-17." (PMID 19014637, 2008). "Our study indicates that the range of cytokines carried by breast tumor cells (stromal and epithelial cells) under PRP supplementation and in co-culture with HUVEC was tumor-subtype and cancer cell-type specific; these cytokines include IL-8, IL-6, TNF-α, and VEGF but are not limited to these ones." (PMID 28187434, 2017). "However, the role of TNF-α in IP-10 production by MCP-7 breast tumor cells is not yet elucidated." (PMID 34572567, 2021). "Importantly, following TNFα stimulation, the cells have acquired the most critical and metastasis-relevant property of EMT, namely increased migratory and invasive properties, by that substantiating the ability of the cytokine to induce EMT in breast tumor cells." (PMID 21486440, 2011). "We estimated the prognostic value of the TNF-α mRNA and the 19 other identified putative TNF-α-inducible gene mRNAs in our series of 96 breast tumors (48 ERα-positive and 48 ERα-negative tumors)." (PMID 21754991, 2011). "TNF-α expression and IL8, IL1A and IL6 expression were only correlated in ER-negative, but not in ER-positive breast tumors." (PMID 21754991, 2011). "We found that addition of TNFα, IFNγ, or TNFα + IFNγ did not significantly alter cell apoptosis or viabilities in cultured HUVECs, LLC cells, or tumour cells derived from MMTV-PyMT breast tumours." (PMID 34285232, 2021). "To determine whether TTP affects NF-кB expression in breast tumor cells, we measured nuclear NF-кB in cells infected with TTP/adenovirus in the presence or absence of TNF-α, a strong inducer of NF-кB." (PMID 26497679, 2015). "Although the expression of TNFα & IL-1β receptors by breast tumor cells was already documented, it is possible that in this specific sub-group of the IDC-with-recurrence patients, the tumor cells do not express the required receptors for TNFα & IL-1β, or express non-signaling receptors." (PMID 21486440, 2011).
cerebral infarction (123 papers, 2007 to 2025). An ischemic condition of the brain, producing a persistent focal neurological deficit in the area of distribution of the cerebral arteries. "For instance, a cerebral infarction leads to an inflammatory state that causes an increased production of TNF alpha by monocytes." (PMID 37065345, 2023). "In this same study, the author confirmed that plasma irisin levels were negatively associated with brain infarct volume, the neurological deficit score, and plasma TNF-α and plasma IL-6 concentrations." (PMID 29720216, 2018). "In this study, we identified TNF-α, age, sex, and cerebral infarction as independent risk factors for the occurrence of POD." (PMID 29137628, 2017). "The inhibition of iNOS, TNF-α, and IL-1β mRNA expression is one of the mechanisms underlying the neuroprotective effects of Caf against cerebral infarction." (PMID 27703487, 2016). "Studies indicate that puerarin treatment in tMCAO rats decreases cerebral infarction volume, enhances neural function, and lowers pro‐inflammatory factors IL‐1β, IL‐6, and TNF‐α, likely via CAP activation." (PMID 40715012, 2025). "After MDSC depletion, the anti-inflammatory and neuroprotective effects of CGRP in cerebral infarction mice were markedly attenuated, as evidenced by increased expression of TNF-α, IL-1β and IL-6 and elevated neuronal apoptosis." (PMID 40963921, 2025). "The higher the concentration of serum TNF-α, the larger the volume of cerebral infarction and the more severe the disease is." (PMID 41471340, 2025). "M1 microglia (with TNF-α or CD86 as markers) generate pro-inflammatory factors, such as TNF-α, IL-1β, IL-6, and interferon-γ, which promote inflammation and exacerbate I/R injury and cerebral infarction." (PMID 39391701, 2024). "Ischemic-hypoxic stimulation in cerebral infarction prompts monocytes to produce inflammatory mediators like interleukin-1 (IL-1), IL-6, IL-8, and tumor necrosis factor (TNF), leading to excessive inflammation that worsens brain tissue damage." (PMID 39030494, 2024). "Serum RIPK1, RIPK3, and TNF‐α levels between the control group and different cerebral infarction volume groups were compared using ANOVA." (PMID 39657719, 2024). "Following a cerebral infarction, activated microglia release vasoactive mediators and pro-inflammatory cytokines such as interleukins (ILs) and tumor necrosis factor-α (TNF-α), which promote significant leukocyte infiltration and initiate neuroinflammation." (PMID 39139557, 2024). "Comparison of serum RIPK1, RIPK3, and TNF‐α levels in patients with different volumes of cerebral infarction." (PMID 39657719, 2024). "The fact that a greater level of TNF-α showed a positive connection between TNF-α levels in CSF and serum and the extent of developing brain infarction cannot be overlooked." (PMID 38213956, 2024). "Ischemic hypoxia changes after cerebral infarction (CI), in which many proinflammatory cytokine such as IL-1, IL-6 as well as cytokines such as TNF-α are significantly released in the body before the inflammatory cell cascade occurs." (PMID 37369997, 2023). "Inflammatory factors TNF-α, IL-6, and IL-1β participate in the process of early inflammatory injury of cerebral infarction." (PMID 36936654, 2023). "Histopathological analysis and measurement of brain infarct size were performed, and cerebral levels of IL-6, IL-10, TNF-α, ICAM-1, NF-κB p65, and total antioxidant capacity were assessed." (PMID 38313176, 2023). "TNF has been proved to be highly expressed in the blood of patients with cerebral infarction in many previous studies." (PMID 36238162, 2022). "The level of IL-12, TNF-α and IL-10 in cerebral infarction tissues was also determined by ELISA method." (PMID 35658867, 2022). "Inhibition of TNF-α decreases activation of immune cells, reduces cerebral infarction, and improves functional outcomes." (PMID 36361836, 2022).
cerebral infarction (continued). "The IL-12 and TNF-α level were significantly decreased while IL-10 were significantly increased in cerebral infarction tissues in CsA@HFn treated MCAO mice." (PMID 35658867, 2022). "Increases the levels of A subunit and B subunit in GABA and IL-1β, IL-6, TNF-α to reduce neurological deficit and cerebral infarct area." (PMID 35548468, 2022). "ELISA results showed that as compared with normal saline, CsA@HFn significantly decreased the levels of IL-12 and TNF-α and increased the level of IL-10 in cerebral infarction tissue of MCAO mice." (PMID 35658867, 2022). "Another study on cerebral infarction also revealed lowered serum levels of IL-6 and TNF-α following rTMS treatment." (PMID 35392634, 2022). "The results showed that as compared with the sham group, IL-12 and TNF-α level in cerebral infarction tissues in MCAO mice were significantly increased." (PMID 35658867, 2022). "Results showed that casticin reduced the volume of the cerebral infarction, mNSS scores, swimming distance, time to find the submerged platform, and serum concentrations of TNF‐α, TGF‐β, IL‐6 in MCAO rats." (PMID 33704926, 2021). "Compared with transplanted MSCs alone, intravenous injection of MSCs combined with NCNCs in mice with cerebral infarction showed higher levels of IL-10, lower levels of TNF-α, and smaller infarct volume." (PMID 34221026, 2021). "The miR-137 downregulated Src reducing cerebral infarction volume by inhibiting release of inflammatory markers such as TNF-α, IL-1, IL-6 and IL-17, p-ERK 1/2, p-38, and p-JNK and also improving cognitive functions in MCAO rats." (PMID 34684090, 2021). "Cross-sectional studies have found that TNF-α, IL-1, IL-6 and CRP are associated with WMH, silent brain infarcts, lower eGFR levels and a higher UACR." (PMID 34072230, 2021). "Serum TNF-α also correlates with brain infarct volume and severity of neurological symptoms as well as reflects the degree of patients' functional disability." (PMID 34433866, 2021). "It is worth mentioning that KCa3.1-KO and/or inhibition have been shown to reduce IL-β1 and TNFα levels in activated microglia after cerebral infarction." (PMID 32150577, 2020). "Pretreatment with insulin alleviated—but glucose augmented—postischemic brain infarction, caspase 3 activity, and TNF-α protein." (PMID 32492962, 2020). "SNHG14 promoted the microglia cells (MCs) classical activation by the inhibition of miR-145-5p, which resulted in the high levels of TNF-α and NO in MCs during cerebral infarction." (PMID 28915705, 2017). "The present study showed that Sino significantly decreased the mRNA levels of pro-inflammatory cytokines, including IL-1β, IL-6, IL-18, and TNF-α, in the tissues surrounding the cerebral infarction." (PMID 27724964, 2016). "Injecting TNF-α in the forebrain led to a dose-dependent increase in cerebral infarct size and neurological function deficits." (PMID 24940430, 2014). "In fact, the induction of iNOS and TNF-α has been reported to be involved in the inflammatory response and the disruption of the blood-brain barrier, leading to the aggravation of brain infarction." (PMID 24594628, 2014). "Contrasting images for intracellular expression of IFN-γ and TNF-α in cerebral infarction patients and healthy volunteers after 24-hour stimulation of CD8+ T lymphocytes by CEF peptide in vitro is shown in." (PMID 23286717, 2013). "After stimulation with virus peptides, CD107a expression and intracellular production of IFN-γ and TNF-α was decreased in patients with cerebral infarction as compared to healthy volunteers (p < 0.01)." (PMID 23286717, 2013). "MSCs transplanted into the brains of cerebral infarction model rats have been reported to affect cytokine release by up-regulating IL-10 and down-regulating TNF-α." (PMID 23049854, 2012).
cerebral infarction (continued). "The level of TNFα in human brain becomes elevated after cerebral infarction and appears sequentially in the infarct core and peri-infarct areas before expression in tissue within the unaffected hemisphere." (PMID 18947406, 2008). "With its chronic upregulation of TNFα in brain, the TNFα-Tg rat is a clinically relevant model of secondary inflammatory changes after cerebral infarction in humans." (PMID 18947406, 2008). "A study showed that acacetin could reduce the expression of NLRP3 and TNF-α to lessen ischemia-reperfusion injury after cerebral infarction." (PMID 38178669, 2024). "It has been reported that anti-TNF therapy could reduce brain infarct volume and edema in an animal model and improve neurological impairments in patients, thus suggesting that TNF signaling may be a vital inflammatory pathway in acute ischemia." (PMID 37234258, 2023). "In addition to brain infarct volume and histopathological assessment, the brain tissues were harvested to evaluate cerebral IL-6, IL-10, TNF-α, ICAM-1, NF-κB p65, and total antioxidant capacity levels." (PMID 36567842, 2022). "In the acute phase of cerebral I/R injury, SP600125 treatment reduced cerebral infarction by inhibiting the expression of inflammatory mediators including TNF-α, IL-1β, IL-6, and matrix metalloproteinase-9 and downregulating the mitochondria-mediated apoptotic pathway in the ischemic area." (PMID 34419138, 2021). "Neuroprotective parameters such as brain infarction, blood–brain barrier disruption, oxidative stress, TNF-α, and IL-1β mRNA expression, along with apoptotic caspase 3 activity, and with neuroprotective, anti-oxidative, anti-inflammatory, and anti-apoptotic effects of quercetin, were reported." (PMID 34206761, 2021). "Third, serum biochemical tests, such as TNF-α levels and intra-arterial oxidative stress, and white matter damage may be related to new cerebral infarctions." (PMID 33551976, 2020). "Additionally, outcomes included neurological deficit score, brain edema, cerebral infarction area, neuronal apoptosis, serum levels of inflammatory factors (TNF-α, IL-6, and IL-1β), and the antioxidant level of body (SOD, MDA, and GSH-Px)." (PMID 30581490, 2018). "Hydroxysafflor yellow A, a major active component of C. tinctorius L. (Hong Hua), reduces cerebral infarction by suppressing cytosolic NF-κBp65 translocation to the nucleus and subsequently downregulates NF-κB-mediated TNF-α, IL-1β, and IL-6 expression in the ischemic area 24 h after permanent MCAo." (PMID 27703487, 2016). "However, microglial synthesis of TNFα within the focal and border zone of cerebral infarction is strain dependent." (PMID 26515746, 2015). "In addition, NMDA receptor antagonist (MK801) and dexmedetomidine treatment has been reported to inhibit the production of TNF-α and improve cerebral infarction in the MCAO model." (PMID 26665003, 2015). "PF reduces cerebral infarction area by inhibiting NFκB, IL-1β, and TNFα." (PMID 23818926, 2013). "According to the present data, the neuroprotection with regard to neurological outcome and brain infarct volume may be partly due to the inhibitory effect of MEA on TNF-α and COX-2." (PMID 24348730, 2013). "During the acute phase of cerebral infarction, blood–brain barrier damage and endothelial cell degeneration occur in patients with acute ischemic stroke (AIS), accompanied by elevated levels of TNF-α and IL-1β." (PMID 40260140, 2025). "The pairwise comparison showed that those with different cerebral infarction volumes all had a much higher content of serum RIPK1, RIPK3, and TNF‐α than the control (p < 0.05)." (PMID 39657719, 2024). "Cerebral levels of IL-6, IL-10, TNF-α, NF-κB p65, and ICAM-1, besides cerebral infarct volume, were significantly elevated in control and vehicle related to sham groups, while total antioxidant capacity was markedly reduced." (PMID 36567842, 2022).
cerebral infarction (continued). "Geniposide has been shown to significantly reduce the area of cerebral infarction and alleviate neuronal damage and necrosis mainly by inhibiting inflammatory signals, including NLRP3, TNF-α, IL-6, and IL-1β." (PMID 34454545, 2021). "Specifically, the levels of ROS and inflammatory factors (TNF-α, IL-6, and IFN-γ) in the brain tissue of rats with cerebral infarction after transplantation of human UC-MSCs labeled with nanoceria were significantly decreased." (PMID 34221026, 2021). "Plasma D-lactate, zonulin, LPS, TNF-α, IFN-γ, and IL-6 were significantly increased after cerebral infarction (P < 0.05)." (PMID 31316450, 2019). "The systematic review and meta-analysis will assess the effect of acupuncture on the expression of inflammatory factors TNF-α, IL-6, IL-1 and CRP in cerebral infarction with up-to-date clinical evidence." (PMID 31192907, 2019). "In the present study, both SGD and clopidogrel inhibited the inflammatory response arising from cerebral infarct and our results demonstrated unequivocally that SGD was a more potent inhibitor of the expression of IL-1β, TNF-α, and MCP-1 than clopidogrel." (PMID 27413737, 2016). "This indicated that severe cerebral infarction itself mildly induced CD8+ T lymphocytes to release IFN-γ and TNF-α." (PMID 23286717, 2013). "Clausen and collaborators demonstrated that IL-1β mRNA and TNF-α mRNA, and TNF-α protein are produced by CD11b+ microglia/macrophages in the penumbra as well as the core of brain infarction." (PMID 22082476, 2011). "To explore potential sources of heterogeneity, we performed subgroup analyses of cerebral infarct volume, CBF, TUNEL and TNF-α according to animal species, anesthetic agent, model type, occlusion duration, drug class, route of administration and timing of administration." (PMID 41551042, 2025). "Studies have shown that Genipin could significantly reduce the area of cerebral infarction and attenuate neuronal damage and necrosis by inhibiting inflammatory factors such as NLRP3, TNF-α, IL-6, and IL-1β." (PMID 39679371, 2024). "A previous study demonstrated that cerebral infarction triggers the TLR signaling activation-induced inflammatory responses, further leading to the expression of NF-κB-mediated inflammatory cytokines, such as IL-1, IL-6, IL-8, and TNF-α." (PMID 35966335, 2022). "In addition, TNF-α plays an important role in the development and progression of ACI, and its content in vivo is positively correlated with cerebral infarction volume and nerve function injury." (PMID 33729386, 2021). "Previous studies have reported that TLR4-mediated signaling causes JNK, p38 MAPK, and NF-κB activation, which induces the production of pro-inflammatory factors, including iNOS, COX-2, TNF-α, and IL-6, in the ischemic area, further exaggerating BBB disruption and cerebral infarction." (PMID 34419138, 2021). "In addition, MLIF decreased cerebral infarction areas and the level of malondialdehyde (MDA), myeloperoxidase (MPO), tumor necrosis factor-alpha (TNF-α), and IL-1β and increased the level of superoxide dismutase (SOD)." (PMID 34220513, 2021). "Furthermore, the effects of YZR extract treatments on cerebral infarction are partially due to the suppression of JNK/NF-κB-mediated iNOS, COX-2, TNF-α, and IL-6 expression in the penumbral cortex at 1 day after reperfusion." (PMID 34419138, 2021). "Additionally, the increases in plasma LPS, TNF-α, IFN-γ, and IL-6 after cerebral infarction coincided with overgrowth of the Bacteroidetes phylum (P < 0.001)." (PMID 31316450, 2019). "CD11b, CCL5 and TNFα expression levels were not significantly elevated at 24 h following cerebral infarction compared to healthy controls." (PMID 25671080, 2014).
cerebral infarction (continued). "The higher levels of proinflammatory tumor necrosis factor (TNF-α), interleukin-6 (IL-6), and interferon-gamma (IFN-γ) in the plasma of focal cerebral ischemia monkeys suggest both intestinal microecological dysregulation and chronic systemic inflammation following cerebral infarction." (PMID 36267243, 2022). "Taking cerebral infarction as a dependent variable (occurrence = 1, no occurrence = 0), the basic clinical data were included in the univariate logistic model analysis, and the results showed that HbAlc, serum TNF-α, and β2-GPI/oxLDL were closely related to the occurrence of DCI (P < 0.05)." (PMID 35898588, 2022).